ARID1A (AT-rich interaction domain 1A)
Diseases named in the same sentence as ARID1A in open-access papers (continued):
Sharing a sentence is not in itself a finding about the gene and the disease.
uterine endometrioid carcinomas (19 papers, 2012 to 2025). "Expression of ARID1A in ARID1A-deficient uterine endometrioid carcinoma cell lines reduced cellular proliferation, the percentage of cells in the S phase, and the growth of tumour xenografts." (PMID 38275587, 2023). "In human uterine endometrioid carcinomas, ARID1A and PTEN are frequently mutated or deleted 7,20,21." (PMID 32483112, 2020). "TCGA data demonstrate that ARID1A is among the most frequently mutated genes among different types of cancer, such as stomach adenocarcinomas (18–31%) or uterine corpus endometrioid carcinomas (34%)." (PMID 33227989, 2020). "Loss of ARID1A protein correlated with the presence of ARID1A mutations was previously reported in ovarian and uterine endometrioid carcinoma." (PMID 33344089, 2020). "ARID1A is also frequently mutated and plays an important role in tumor progression in uterine endometrioid carcinoma." (PMID 29451900, 2018). "ARID1A mutation or loss is found in 25% to 50% of endometrioid endometrial adenocarcinoma." (PMID 38275587, 2023). "Thus, loss of ARID1A appears to be an early event in the carcinogenesis of endometrioid uterine carcinomas, and the association with deep myometrial infiltration may suggest importance for invasiveness." (PMID 35269800, 2022). "ARID1A, in particular, has been shown to function as a tumor suppressor in various malignancies, such as ovarian clear cell, ovarian endometrioid and uterine endometrioid carcinomas." (PMID 37373240, 2023). "Histopathological, clinical, and molecular features of tumors from Arid1a/Pten co-deleted (iPAD) mice closely resembled human uterine endometrioid carcinomas." (PMID 32483112, 2020).
gastric tumors (18 papers, 2012 to 2025). "Earlier studies have demonstrated that ARID1A mutations were more frequent in Gastric tumors, especially with microsatellite instability and Epstein-Barr virus infection." (PMID 34924820, 2021). "ARID1A mRNA and protein expression were reported to be significantly lower in gastric tumor tissues compared to normal gastric adjacent mucosa." (PMID 26334097, 2015). "Normal gastric mucosa and gastric tumor tissues were compared for ARID1A, CDH1, c-MET and PIK3CA mRNA expression using RT-qPCR." (PMID 26334097, 2015). "ARID1A had the highest ratio of LOF to benign mutations among ERGs, and was mutated in 25.4% of urothelial bladder tumors, 31.1% of gastric tumors, and 33.5% of endometrial tumors." (PMID 26110843, 2015). "Loss of ARID1A expression, primarily due to frameshift mutations, is correlated with poorer outcomes, particularly in mismatch repair‐proficient, EBV‐negative cases and proximally located, larger gastric tumors." (PMID 40926327, 2025). "ARID1A substitutions that we identified in gastric tumors, not annotated in human mutation databases, namely p.R2236C, p.Q1415H, and p.P1710L, are of interest since they can lead to deregulation of molecular mechanisms important for cancer progression." (PMID 34572812, 2021). "Normal gastric mucosa, gastric tumor, and peritumoral tissues were compared for RUNX3 and ARID1A protein expression." (PMID 27566570, 2016). "Consistent with the quantitative real-time PCR results, a decrease in ARID1A expression was seen in 13 (52%) of the gastric tumor tissues compared with matched adjacent non-tumor tissues (P = 0.0015)." (PMID 22808142, 2012).
serous carcinoma (18 papers, 2014 to 2025). "We found one overlapping variant between the surgical specimens and the pipelles (10%), which was an ARID1A variant in a woman with high-grade serous carcinoma stage 3B who had this variant in all specimens but the Pap smear." (PMID 36384753, 2022). "In serous carcinoma, ARID1A loss has been reported in 9–14% of cases and has been suggested as a useful marker in the distinction between high-grade EEC and serous carcinoma." (PMID 41001390, 2025). "Our study reports a relatively low frequency of ARID1A in high-grade EEC (20%) compared to serous carcinoma (11.1%), hence limiting its use in making this distinction (p = 0.64871)." (PMID 41001390, 2025). "However, endometrial CCC differs from serous carcinoma by the presence of mutations in PTEN and ARID1A and microsatellite instability." (PMID 33143664, 2020).
endometrioid ovarian cancer (17 papers, 2015 to 2026). "ARID1A is a tumour suppressor gene that is frequently mutated in clear cell and endometrioid carcinomas of the ovary and endometrium and is an important clinical biomarker for novel treatment approaches for patients with ARID1A defects." (PMID 29659191, 2018). "Two independent studies carried out in 2010 showed that clear cell and endometrioid ovarian cancers were due to somatic mutations in AT-rich interaction domain-1A (ARID1A)." (PMID 29743986, 2018). "In accordance with these results, activation of oncogenic KRAS and PI3K pathways and inactivation of tumor suppressor genes PTEN and ARID1A are suggested pathogenic mechanisms for clear-cell and endometrioid ovarian cancers." (PMID 26413541, 2015). "Using both institutional genomic data, and data from the NCI sponsored cancer genome atlas, ARID1A mutations were frequently identified as mutated tumor suppressor genes, in clear cell and endometrioid ovarian cancer as well as low grade endometrioid endometrial cancer." (PMID 29093822, 2017). "For example, ARID1A is frequently mutated in OCCC and endometrioid ovarian cancer (EnOC) but rarely mutated in HGSOC and mucinous ovarian cancer (MOC)." (PMID 39272926, 2024). "These clinical data show that PARP inhibitors provide no clinical benefit in ARID1A-mutated, high-grade serous or endometrioid ovarian cancer and warrants further investigation." (PMID 29669295, 2018).
gastric adenocarcinoma (17 papers, 2013 to 2025). "In a previous study involving 489 consecutive primary gastric adenocarcinomas, abnormal ARID1A expression (reduction or loss) was observed in 109 cases and frequent MMR deficiency was reported." (PMID 38041544, 2023). "Loss of ARID1A expression was observed in 22.5% of gastric adenocarcinomas in two separate patient cohorts and was positively correlated with the loss of expression of MMR proteins." (PMID 38041544, 2023). "Investigation of GC using NGS previously revealed that 47% of gastric adenocarcinomas were characterized by mutations of chromatin remodeling genes, and somatic mutations of ARID1A had a high frequency, as it was in our study." (PMID 34572812, 2021). "For example, in gastric adenocarcinoma, ARID1A mutations are correlated with simultaneous PIK3CA mutations in 8% of tumors." (PMID 34671561, 2021). "An analysis of ARID1A mutations found in cBioPortal (1036 mutations), at the time of this writing, showed that a stomach adenocarcinoma (TCGA-FP-8631-01) contained the same ARID1A mutation found in the 105C line." (PMID 33153119, 2020). "Consistently, in uterine corpus endometrial carcinoma, stomach adenocarcinoma and colon adenocarcinoma, compared with ARID1A wild-type tumors, ARID1A-mutated tumors displayed a significantly lower levels of genomic instability as determined by CNA." (PMID 31492885, 2019). "Complementary evidence from MEXPRESS further confirmed this anti-correlation pattern, particularly emphasizing that hypermethylation of CpG islands within the ARID1A promoter region was inversely associated with gene expression in gastric adenocarcinoma specimens." (PMID 41215803, 2025). "Furthermore, stratification of patients by ARID1A mutational status confirmed this relationship, where some ARID1A-mutated cancer subtypes (e.g., stomach adenocarcinoma—STAD) appear to upregulate KEAP1 compared to wild-type." (PMID 39272807, 2024). "This study explored the significance of ARID1A expression in TCGA subtypes of gastric adenocarcinoma." (PMID 37366273, 2023). "We collected 1248 postoperative patients with gastric adenocarcinoma, constructed tissue microarrays, performed immunohistochemistry for ARID1A, and obtained correlations between ARID1A and clinicopathological variables." (PMID 37366273, 2023). "In recent years, gastric adenocarcinoma with ARID1A abnormalities has received increasing attention as a distinct tumor entity." (PMID 37366273, 2023). "Currently, there are many studies on ARID1A in gastric adenocarcinoma, while the significance of ARID1A in the TCGA molecular subtypes of gastric adenocarcinoma has not been studied in depth." (PMID 37366273, 2023). "Furthermore, the analysis of pan-cancer TCGA data revealed a mild but significant correlation where some ARID1A-mutated tumor subtypes present elevated KEAP1 mRNA levels (e.g., stomach adenocarcinoma—STAD, and colon adenocarcinoma—COADREAD)." (PMID 39272807, 2024). "Large‐scale studies are needed to explore the complete molecular profile of gastric adenocarcinoma, confirm the prognostic significance of TCGA classification and ARID1A negative expression, and ultimately achieve risk stratification and more individualized patient management." (PMID 37366273, 2023).
gastric adenocarcinoma (continued). "In summary, we detected the IHC expression of ARID1A in gastric adenocarcinoma and explored the impact of ARID1A negative expression on prognosis and immune infiltration in combination with TCGA molecular classification." (PMID 37366273, 2023). "Herein, we explored the prognostic and immune infiltration significance of ARID1A negative expression in TCGA subtypes in 1248 patients with gastric adenocarcinoma." (PMID 37366273, 2023). "ARID1A inactivation is related to lymphatic infiltration, lymph node metastasis, poor prognosis, and MMR defects in gastric adenocarcinoma." (PMID 34671561, 2021).
glioma (17 papers, 2014 to 2025). A benign or malignant brain and spinal cord tumor that arises from glial cells (astrocytes, oligodendrocytes, ependymal cells). "Having studied the effect of ARID1A mutation on glioma in clinical tumor samples and at the in vitro cytological level, we further investigated the effect in experimental animals." (PMID 38600891, 2024). "The mutation frequency of high‐frequency mutated genes in the WHO grade 4 glioma patients in the validation cohort was broadly similar to the results in the dataset, with a mutation frequency of 63% in ARID1A." (PMID 38600891, 2024). "Deep sequencing targeting DNA damage repair pathways identifies ARID1A as a prognostic biomarker for gliomas and its mutation alters SWI/SNF stability increasing the malignant phenotype of GBM and mediating chemoresistance." (PMID 38600891, 2024). "Upon integrating deep targeted sequencing data, we observed that the ARID1A gene was significantly more frequently mutated in WHO grade 4 gliomas than in WHO grades 1–3 gliomas, a phenomenon that ignited our research curiosity." (PMID 38600891, 2024). "In our sequencing study cohort, we analyzed the relationship between ARID1A mutations and the prognosis of glioma patients and found that ARID1A mutations were negatively correlated with the prognosis of glioma patients (p = 0.0217)." (PMID 38600891, 2024). "Meanwhile, 10/14 of gliomas harbored NS mutations in Arid1a and 43% of those were orthologous to COSMIC variants." (PMID 38232086, 2024). "In gliomas, ARID1A mutations in WHO grade 3 oligodendrocyte tumors are linked to poorer progression‐free survival, yet the role of ARID1A in GBM remains to be fully unraveled." (PMID 38600891, 2024). "In conclusion, these results suggest that ARID1A mutations may be more common in WHO grade 4 gliomas and that deep‐targeted gene sequencing may provide valuable clues for further investigation of glioblastoma biomarkers in the future." (PMID 38600891, 2024). "The analysis of sequencing mutation results of deep targeted genes in integration revealed that ARID1A gene mutation occurs frequently in glioblastoma and alteration of ARID1A could affect the tolerance of glioma cells to temozolomide treatment." (PMID 38600891, 2024). "To further elucidate the underlying mechanisms, we compared the alterations in cell cycle and DNA damage repair proteins associated with wild‐type ARID1A, ARID1A KD, and ARID1A‐P16 deletion models to those in control glioma lines, following treatment with 200 μM TMZ, using Western blotting." (PMID 38600891, 2024). "Consistent with this proposal, a search of cancer genomics datasets revealed a co-occurrence of AT-rich interaction domain 1A (ARID1A) mutations with DAXX mutations or copy number alterations in glioma and pancreatic neuroendocrine tumors (PanNETs), among others." (PMID 31895940, 2020). "Mutations at the ARID1A locus alter the stability of the SWI/SNF complex, leading to changes in transcriptional regulation in glioma cells." (PMID 38600891, 2024). "Through in‐depth deep targeted gene sequencing analysis of glioma (GBM) tissues, we identified five high‐frequency loci for mutations in the ARID1A gene in GBM patients." (PMID 38600891, 2024). "In order to deeply investigate the function of ARID1A in glioma (GBM) cells, we first explored the relationship between ARID1A and the malignant biological behaviors of GBM by characterizing cell cycle‐related proteins." (PMID 38600891, 2024). "The SWI/SNF complex affects histone modification in cells to further explore the effect of ARID1A on glioma cells through histone modification." (PMID 38600891, 2024). "Downregulation of ARID1A significantly promoted the expression of glioma cell cycle‐related proteins and accelerated cell cycle progression." (PMID 38600891, 2024). "In the TCGA dataset, alterations were detected in ARID1A in low grade glioma (SNV: 3.9%, 11/283; deletion: 0.4%, 1/283) and glioblastoma (SNV: 0.7%, 2/281)." (PMID 31217899, 2019).
glioma (continued). "Our data suggest that not only mutations, but also copy number alterations and expression of ARID1A should be investigated to confirm its oncogenic role in gliomas." (PMID 26524630, 2015). "In summary, our results propose that ARID1A not only acts as a predictive biomarker in gliomas but also that its deletion, by undermining the stability of the SWI/SNF complex, may cause gliomas to exhibit more malignant features." (PMID 38600891, 2024). "The ARID1A gene is a critical predictive biomarker for glioma." (PMID 38600891, 2024). "In addition, the mutation in the 16th amino acid of the ARID1A protein reduced the activity of the SWI/SNF complex by affecting the stability of BRG1, which may promote glioma progression and the development of TMZ resistance." (PMID 38600891, 2024). "Overexpression of the genes whose transcripts act as potential targets fordysregulated miRNAs in the IDHmut and IDHwt groups is observed in moreaggressive glioma types: FKBP9 – CREB3L4, MCM4, MCM6, PSMB2, ARID1A, ARL4C, GRPEL2, and C9orf64." (PMID 39539523, 2024). "The most commonly recurrent deletion events on chromosome 1p (ARID1A, CDKN2C, FUBP1) and chromosome 19q (CIC) were observed in gliomas of CYT-low cohort." (PMID 31428092, 2019). "By targeting the regulation of ARID1A and SWI/SNF complexes, it may be feasible to develop more effective therapeutic approaches to enhance the survival and quality of life of glioma patients." (PMID 38600891, 2024). "In conclusion, ARID1A may regulate the cell cycle state and apoptosis of GBM cells, and ARID1A KD may enhance the therapeutic resistance response of GBM to TMZ, thereby promoting the ability of glioma cells to resist TMZ in vitro." (PMID 38600891, 2024). "The results showed that ARID1A KD effectively promoted tumor growth with more malignant biological characteristics, whereas TMZ treatment was not effective in inhibiting tumor proliferation of gliomas in ARID1A KD mice." (PMID 38600891, 2024).